SIRT1 (sirtuin 1)
Diseases named in the same sentence as SIRT1 in open-access papers (continued):
Sharing a sentence is not in itself a finding about the gene and the disease.
thyroid cancer (9 papers, 2016 to 2026). "Some studies show that transgenic Sirt1 expression is oncogenic in murine thyroid and prostate carcinogenesis initiated by Pten-deficiency, and that SIRT1 stabilises the c-MYC protein in cultured thyroid cancer cells." (PMID 27793039, 2016). "SIRT1 was acknowledged as a direct downstream target of miR-212, which hindered the proliferation and promoted the apoptosis of thyroid cancer cells by negatively regulating SIRT1." (PMID 35136826, 2022). "Particular attention should be paid to the role of miRNAs in regulating SIRT1 levels (miR-212 in thyroid cancer; miR-494, miR-138-5p, miR-601, and miR-217 in PC; miR-204 in HCC)." (PMID 30319549, 2018). "SIRT1 is a direct target of miR-212 and is inversely correlated to miR-212 expression in thyroid cancer tissues (42 samples of human thyroid cancer)." (PMID 30319549, 2018). "The impact of enzymatic SIRT1 activation or inhibition on thyroid cancer cell growth in vitro is poorly examined." (PMID 30271381, 2018). "Our results therefore indicate SIRT1 to be a crucial component of VD's anti-proliferative signals in thyroid cancer cells and immune cells." (PMID 30271381, 2018). "Significant differences were observed in the levels of HIC1 and SIRT1 protein expression by Western blot analysis in the thyroid cancer tissues and adjacent normal tissues." (PMID 27793057, 2016). "The mRNA expression levels of HIC1 and SIRT1 were measured in samples from thyroid carcinomas and adjacent normal thyroid tissues." (PMID 27793057, 2016). "In summary, hypermethylation of the HIC1 promoter in thyroid papillary carcinoma might contribute to aberrant expression of HIC1/SIRT1, which in turn promotes thyroid cancer." (PMID 27793057, 2016). "Moreover, TSPYL2 may inhibit thyroid cancer progression by modulating SIRT1/AKT signaling." (PMID 40141028, 2025). "Compared with normal thyroid cancer cells, the expression of SIRT7 was significantly increased in DTC, and the overexpression of SIRT7 and SIRT1 conferred resistance to DTC cells." (PMID 35136826, 2022). "The evidence available in thyroid cancer confirms that c-MYC and SIRT1 are valuable therapeutic targets, encouraging translational researches aimed at the related pathways." (PMID 30319549, 2018). "Tissue analyses confirmed that the level of HIC1 expression in thyroid carcinoma tissue was greater than in normal tissue, and that within thyroid carcinomas there was a negative correlation between HIC1 and SIRT1 expression." (PMID 27793057, 2016).
acute lymphoblastic leukemia (8 papers, 2015 to 2025). Leukemia with an acute onset, characterized by the presence of lymphoblasts in the bone marrow and the peripheral blood. "Indeed, when exposed to 25 μM of 13b, acute lymphoblastic leukemia (ALL) cells MOLT‐4 were found to overexpress the same subset of genes that were upregulated following SIRT1 silencing by RNA interference." (PMID 39215785, 2025). "Similarly, inhibition of SIRT1 in acute lymphoblastic leukemia (ALL) also inhibits the Wnt/β‐catenin signaling pathway resulting in elimination of ALL stem/progenitor cells." (PMID 28994177, 2017). "Indeed, SIRT1 is not only elevated upon treatment with AG, but interference with AMPK/SIRT1 signaling prevented the induction of autophagy in lymphoblastic leukemia cells." (PMID 33381011, 2020).
amyloid (8 papers, 2015 to 2024). "Studies have linked a decrease in SIRT1 to increased amyloid plaques, uncontrolled neuroinflammation, and even tau pathology." (PMID 36230925, 2022). "In addition, the anti-aging gene Sirtuin 1 can regulate neuron proliferation in various populations and is linked to cardiovascular disease with effects on inflammation, energy, cognition, glucose/cholesterol levels, amyloidosis, and neurogenesis." (PMID 35087849, 2021). "Studies with animal models have shown that the deposition of β-amyloid plaques in the brain of model mice is inversely correlated with SIRT1 levels." (PMID 39273436, 2024). "This role of SIRT1 in AD is apparently connected to CR/DR, which reduces Aβ generation and amyloid plaque deposition in the brain of Tg2576 transgenic AD mice and primate." (PMID 25805970, 2015). "Sirtuin 1 is a critical nuclear deacetylase that participates in regulating the transcription of various transcription factors and cellular signal transduction proteins, involving inflammation, neurogenesis, glucose/cholesterol metabolism, and amyloidosis." (PMID 38384936, 2024). "From these findings, we propose that CR treatment might improve the inflammatory state and mitochondrial functions via the SIRT1-PGC-1α pathway in mice with amyloidosis." (PMID 28225824, 2017).
Burkitt lymphoma (8 papers, 2011 to 2024). A rare form of malignant mature B-cell non-Hodgkin lymphoma. "Interestingly, treatment of BCL6-expressing Burkitt lymphoma cells and Burkitt lymphoma xenograft mice with a dual SIRT1 and SIRT2 inhibitor, cambinol, produced a potent antitumor effect." (PMID 24259290, 2013). "In a study of Burkitt lymphoma, it was demonstrated that the use of LDH-specific inhibitors could result in a reduction in MYC protein levels through NAD/NADH-dependent inhibition of sirtuin-1, thereby depriving BL cells of the most important survival signal." (PMID 39464313, 2024). "In Burkitt lymphoma cells, the LDH inhibitor galloflavin reduces cellular NAD levels and leads to the inhibition of sirtuin-1." (PMID 37915411, 2023). "As confirmed in previous studies, sirtuin-1 inhibition leads to a reduction in MYC protein levels, depriving Burkitt lymphoma cells of a crucial survival signal." (PMID 37915411, 2023). "Intriguingly, a follow-up study with cambinol-based dual SIRT1/2 inhibitors demonstrated a strong correlation between SIRT2 inhibitory activity and cytotoxicity in Namalwa Burkitt lymphoma cell line." (PMID 31973227, 2020). "Cambinol, an inhibitor of SIRT1 and SIRT2, promotes apoptosis Burkitt lymphoma xenografts in mice." (PMID 22275802, 2012). "Previously, we described the discovery of a dual SIRT1/SIRT2 inhibitor called cambinol (IC50 56 and 59 μM, respectively), which showed cytotoxic activity against cancer cells in vitro and a marked anti-proliferative effect in a Burkitt lymphoma mouse xenograft model." (PMID 31973227, 2020).
cataract (8 papers, 2019 to 2025). Partial or complete opacity of the crystalline lens of one or both eyes that decreases visual acuity and eventually results in blindness. "Numerous studies have also linked Sirt1 dysfunction to ocular diseases, including cataracts and age-associated macular degeneration." (PMID 39404375, 2024). "We comprehensively investigated the downregulation of SIRT1 expression and the upregulation of p66Shc expression in human cataract samples, UVB‐induced rat cataract models, and UVB‐treated LEC." (PMID 40569566, 2025). "Our data indicated that cell senescence was reduced and cataracts were delayed upon treatment with RGNPs through activating the Sirt1/Nrf2 signaling pathway." (PMID 36678523, 2022). "Consistent with the in vitro experimental results, the protein expression levels of Sirt1 and Nrf2 were significantly decreased in the cataract group and significantly increased in the RGNP groups compared to the Res group." (PMID 36678523, 2022). "Notably, studies have shown that decreased SIRT1 activity can lead to cataracts in SD rats under UVB irradiation." (PMID 40569566, 2025). "Similarly, in our study, we found a significant increase in the expression level of the SIRT1 gene in the older cataract patients." (PMID 31287252, 2019). "Although direct studies on the autophagic role of spermidine in age-related cataracts have not been conducted, there is indirect evidence regarding its positive regulation of Sirt1." (PMID 39404375, 2024).
Cirrhosis (8 papers, 2021 to 2025). A chronic disorder of the liver in which liver tissue becomes scarred and is partially replaced by regenerative nodules and fibrotic tissue resulting in loss of liver function. "So, it is noteworthy to explore the effects of the administration of a highly absorbed intestinal SIRT1 activator such as resveratrol on the coexisting TNFα-mediated intestinal and renal pathogenic changes as well as renal dysfunction in cirrhosis." (PMID 33513830, 2021). "This study explores the impacts of intestinal SIRT1 deficiency and TNFα-mediated intestinal abnormalities on the development of cirrhosis-related renal dysfunction." (PMID 33513830, 2021). "Through sirT1-autophagy pathway, it can relieve the optometritic stress of high fat endoplasm to prevent cirrhosis." (PMID 36700474, 2022). "Agents that can restore intestinal SIRT1 have the potential to improve the inflammation-derived TNFα-mediated renal dysfunction in advanced cirrhosis." (PMID 33513830, 2021). "In mice with advanced cirrhosis, the expression of intestinal SIRT1 is involved in the linkage between intestinal dysbiosis and vasoconstriction/hypoperfusion-related renal dysfunction through the crosstalk between intestinal/renal TNFα-related pathogenic inflammatory signals." (PMID 33513830, 2021). "In addition to supporting the previous observation regarding the crosstalk between hepatic SIRT1 and TNFα, this study suggests a link between SIRT1−TNFα crosstalk and intestinal SIRT1-related effects and renal dysfunction of cirrhosis." (PMID 33513830, 2021). "The combination of quercetin and metformin has also been found to reduce cirrhosis by stimulating autophagy and reducing inflammatory cytokines via the cAMP/AMPK/SIRT1 signaling pathway." (PMID 40230695, 2025). "Nonetheless, the contribution of the crosstalk between intestinal and renal TNF and SIRT1 signals in the severe renal dysfunction of cirrhosis has not yet been explored." (PMID 33513830, 2021). "However, unlike in the stages of fibrosis or cirrhosis, during the development of HCC, SIRT1 often exhibits pro-oncogenic properties and is associated with poor prognosis." (PMID 41281762, 2025).
Duchenne muscular dystrophy (8 papers, 2014 to 2025). Duchenne muscular dystrophy (DMD) is a neuromuscular disease characterized by rapidly progressive muscle weakness and wasting due to degeneration of skeletal, smooth and cardiac muscle. "Mechanistically, resveratrol-induced SIRT1 down-regulates p300 through augmentation of its ubiquitination and proteasomal degradation, further indicating the pivotal role of elevated p300 in pathogenesis of cardiomyopathy, the major cause of death of Duchenne muscular dystrophy patients." (PMID 32765954, 2020). "We also observed that SIRT1 overexpression counteracts muscle atrophy, a hallmark of aging muscle, and the muscle degenerative disease Duchenne muscular dystrophy (DMD)." (PMID 25032964, 2014). "Notably, SIRT1 overexpression significantly alleviates muscle pathology associated with Duchenne Muscular Dystrophy (DMD)." (PMID 38148899, 2023). "The main aim of our systematic review is to assess the correlation between Duchenne muscular dystrophy and the enzyme SIRT1." (PMID 34205021, 2021). "Quercetin also proved to be a good activator of SIRT1 with beneficial effects against Duchenne muscular dystrophy." (PMID 34205021, 2021). "The cardioprotective effect of resveratrol stems from induction of deacetylase SIRT1, which suppresses cardiac hypertrophy and fibrogenesis and thus improves cardiac diastolic function in the murine model of Duchenne muscular dystrophy." (PMID 32765954, 2020). "We thus crossed SIRT1 Tg-4140 and Tg-4145 mice to mdx mouse model, which is a severe model of Duchenne muscular dystrophy." (PMID 25032964, 2014). "Studies in Duchenne muscular dystrophy mouse models indicate that calorie restriction increases regenerative capacity in injured muscles and enhances satellite cell transplantation efficiency, likely through upregulating SIRT1 expression." (PMID 38904020, 2024). "To examine whether increased activity of SIRT1 protects from muscular dystrophy, a muscle degenerative disease, we crossed SIRT1 muscle transgenic mice to mdx mice, a genetic model of Duchenne muscular dystrophy." (PMID 25032964, 2014).
fetal growth restriction (8 papers, 2020 to 2024). A fetus that does not grow beyond the 10th percentile of conventionally accepted weight for gestational age. "Metformin can also reduce the blood pressure in SIRT1+/− mice but causes fetal intrauterine growth restriction, which increases fetal morbidity and mortality." (PMID 35327614, 2022). "Similarly, an inverse association between SIRT1 and IGF-1 has also been observed in cases of intrauterine growth restriction (IUGR)." (PMID 39062007, 2024). "Since PE can cause fetal growth restriction (FGR), we analyzed the weight of the live fetus in SIRT1flox/flox and SIRT1+/− groups, showing that the weight of the live fetus was dramatically lower in SIRT1+/− mice (SIRT1+/− vs. WT: 0.7803 ± 0.1651 vs. 0.8559 ± 0.1585 g)." (PMID 35327614, 2022). "Recently, a decreasing trend of SIRT1 and activated AMPK/PGC-1a protein have been found in PE placentas, and inhibited SIRT1 and PGC-1a have been found in a group of patients with both intrauterine growth restriction and PE." (PMID 35295266, 2022).
Hypercholesterolemia (8 papers, 2010 to 2024). An increased concentration of cholesterol in the blood. "We observed that hypercholesterolemia increased significantly serum cholesterol and triglycerides, reduced significantly liver SIRT1, and, in turn, induced hepatic oxidative stress in untreated ApoE−/− mice with respect to control mice." (PMID 29516009, 2018).
male infertility (8 papers, 2021 to 2025). The inability of the male to effect fertilization of an ovum after a specified period of unprotected intercourse. "In addition, SIRT1-deficient mice induce male infertility by inducing spermiogenesis disruption, sperm morphological abnormalities and the inability to display hyperactivated motility." (PMID 37906355, 2024). "Sirt1 deacetylates cortactin to drive in vitro GnRH neuronal migration, and GnRH neurons in Sirt1−/− mice loss migration from vomeronasal organ to colonize in hypothalamus, leading to hypogonadotropic hypogonadism reminiscent of human congenital Kallmann’s Syndrome that causes male infertility." (PMID 35067179, 2022). "Sirtuin 1 (SIRT1) is also an intriguing research topic in male infertility." (PMID 38913627, 2024). "In addition, lower levels of sirtuins such as SIRT1 and SIRT3 in seminal plasma or within sperm can exacerbate damage to sperm DNA, thus making it unfit for proper fertilization, leading to male infertility." (PMID 38255792, 2024). "Hence, it can be concluded that lower seminal plasma levels of SIRT1, SIRT3, TAC, SOD and catalase may result in increases in oxidative stress, which impacts on various sperm parameters, thereby leading to male infertility." (PMID 38255792, 2024).
mastitis (8 papers, 2022 to 2026). Inflammation of breast tissue during lactation or postpartum due to an obstructed duct or infection. "Our previous studies in dairy cattle unveiled SNP variants in LAP3 and SIRT1 genes that affected the estimated breeding value of milk production traits and clinical mastitis in Sahiwal and Karan Fries dairy cattle." (PMID 38500063, 2024). "In mastitis, SIRT1 activation helps to reduce intracellular iron content and inhibit lipid peroxidation, thereby reducing ferroptosis and protecting breast tissue from damage." (PMID 40109363, 2025). "Nrf2 is one of the key downstream target genes of SIRT1 and has been shown to protect against mammary injury during mastitis by blocking ferroptosis." (PMID 38611801, 2024). "Dios was found to upregulate the expression of SIRT1 and Nrf2, providing a new idea for the clinical treatment of S. aureus-induced mastitis." (PMID 38611801, 2024). "Taken together, these results suggest that HEX ameliorates S. aureus-induced mastitis by the PPARα-SIRT1-NF-κB axis." (PMID 37948460, 2023). "In conclusion, SAA protected S. aureus‐induced mastitis through suppressing inflammation and ferroptosis by activating SIRT1/Nrf2 pathway." (PMID 37644785, 2023). "In terms of the existing evidence of melatonin in the role of SIRT1, the specific effects and pertaining molecular mechanisms of melatonin regulating SIRT1 under the condition of mastitis deserve further exploration." (PMID 35740004, 2022). "SIRT1-mediated ferroptosis plays an important role in the pathological process of mastitis." (PMID 40109363, 2025). "In conclusion, our study demonstrates that SSA could alleviate S. aureus‐induced mastitis in mice by inhibiting ferroptosis and inflammation via the SIRT1/Nrf2 pathway." (PMID 37644785, 2023). "Collectively, metformin combats resistant E. coli mastitis through a dual mechanism: disrupting biofilm-dependent bacterial persistence and reprogramming host immunometabolism via AMPK/SIRT1-mediated epigenetic regulation." (PMID 41790864, 2026). "Collectively, HEX alleviated inflammatory response via PPARα-SIRT1-NF-κB axis in vitro and HEX also rescued S. aureus-induced mastitis in a dose-dependent manner in vivo." (PMID 37948460, 2023).